Y_RNA (Y RNA )
Gene: Miscellaneous RNA gene on chromosome 17 (7,266,055 to 7,266,166, reverse strand). Ensembl gene ENSG00000202251.
Homologues: Orthologues: chimpanzee Y_RNA (99% identical), macaque Y_RNA (91% identical). Paralogues in human: Y_RNA (82% identical), Y_RNA (81% identical), RNY1 (79% identical), Y_RNA (79% identical), RNY1P2 (79% identical), RNY1P5 (79% identical), Y_RNA (78% identical), Y_RNA (77% identical), RNY1P6 (76% identical), Y_RNA (76% identical), Y_RNA (75% identical), Y_RNA (74% identical), and 91 more.